IL13 (interleukin 13)
Diseases named in the same sentence as IL13 in open-access papers (continued):
Sharing a sentence is not in itself a finding about the gene and the disease.
asthma (continued). "Recent studies have provided substantial evidence that Th2 cell-related cytokines, such as IL-4, IL-5 and IL-13, play a pivotal role in the development and severity of asthma." (PMID 40323927, 2025). "Th2 cells subsequently produce the characteristic cytokines of type 2 inflammation—IL-4; IL-5; and IL-13—which coordinate the allergic and eosinophilic responses in asthma." (PMID 40564060, 2025). "For instance, necrotizing pneumonia similar to our case has been reported in a 61-year-old man with severe asthma receiving dupilumab, an anti-IL-4/IL-13 monoclonal antibody, who developed bilateral cavitary lesions confirmed on computed tomography." (PMID 41567916, 2025). "H2L5186303, an antagonist of LPA2, suppresses increases in eosinophil counts and Th2 cytokine (IL-5 and IL-13) in BALF in a murine model of asthma after allergen challenges." (PMID 40001485, 2025). "Two major endotypes are T‐helper type 2 (TH2)‐high asthma, characterized by eosinophilic inflammation and elevated cytokines (IL‐4, IL‐5, IL‐13, IgE), and TH2‐low asthma with neutrophilic or pauci‐granulocytic profiles and corticosteroid‐resistance." (PMID 41185941, 2025). "Several biologics targeting IL-13 have been developed for the treatment of asthma, particularly for patients with type 2 inflammation." (PMID 40564060, 2025). "Th2 cells produce IL-4 and IL-13, key cytokines in asthma inflammation, while Th17 cells produce IL-17, which is closely related to the pathogenesis of neutrophilic and eosinophilic asthma." (PMID 41293155, 2025). "Compared with control mice, IL-4, IL-5, and IL-13 concentrations were significantly increased in mice with asthma." (PMID 40343297, 2025). "Type 2high asthma, which accounts for the majority of asthma cases, is driven by Th2 cells that produce cytokines such as IL-4, IL-5, and IL-13." (PMID 41145900, 2025). "TH2 cytokines mediate key asthma characteristics: IL-5 for tissue eosinophilia, IL-13 for bronchial hyperresponsiveness, and IL-4 plus IL-13 for goblet cell metaplasia." (PMID 40732309, 2025). "IL‐13 has been shown to promote eosinophil recruitment, which is in line with our observation of higher numbers of airway eosinophils in females with asthma compared to males." (PMID 40022441, 2025). "Dupilumab is a monoclonal antibody targeting the interleukin-4 (IL-4) and interleukin-13 (IL-13) receptor complex and is used for the treatment of atopic dermatitis (AD), severe asthma, chronic rhinosinusitis with nasal polyps, and prurigo nodularis (PN)." (PMID 40322378, 2025). "Biologic therapies targeting cytokines IL-4, IL-5, and IL-13 have been shown to provide benefits to asthmatic patients over currently existing asthma treatments." (PMID 39844912, 2025). "Clinical evidence supports the efficacy of IL-4/IL-13 pathway inhibition in reducing exacerbations in both asthma and COPD." (PMID 41002723, 2025). "Both asthma and CRS have implicated type 2 inflammation pathways of innate immunity, including IL-4, IL-6, IL-13, and the TSLR pathway." (PMID 41213931, 2025). "For example, methylation signatures at IL13, POSTN, and CLCA1 loci in nasal epithelium have been associated with Th2-high asthma phenotypes and linked to disease severity." (PMID 40806756, 2025). "Lunsekimig is a bispecific NANOBODY® that blocks both TSLP and IL-13 signaling in development for asthma and COPD." (PMID 41409758, 2025). "It is known that epithelial cells and innate lymphoid cells in airways of patients with asthma have an enhanced production of IL-13, IL-25, and IL-33 and a deficit in type I and III interferon responses that are needed for effective antiviral clearance." (PMID 39507925, 2025). "After establishing the asthma model, the levels of IL-5, IL-13, MCP-1, TNF-α, and eotaxin significantly increased in the PLA group compared with those in the NOR group (P < 0.01), while the IL-10 level significantly decreased by 42.0% (P < 0.01)." (PMID 39820222, 2025).
asthma (continued). "The effects of prolonged IL-4 and IL-13 stimulation on alarmin and antiviral responses were studied in BECs from healthy and asthma donors exposed to a combination of IL-4 and IL-13 for 10 days prior to infection with RV." (PMID 40370530, 2025). "IL-4 released from allergen-bound Th2 cell stimulates the release of IL-4, IL-5, and IL-13, promotes IgE production from B cells, and accelerates inflammation in asthma patients." (PMID 40323927, 2025). "Biologic agents, including monoclonal antibodies targeting interleukin-13 (IL-13) such as dupilumab, have shown efficacy in reducing periostin levels and improving asthma control in patients with severe eosinophilic asthma." (PMID 40649123, 2025). "Studies indicate that IL-4 and IL-13, key cytokines in asthma, disrupt TJ components, impairing barrier function in asthma." (PMID 41303221, 2025). "Periostin expression is induced in airway epithelial cells by Th2 cytokines, particularly interleukin (IL)-4 and IL-13, pivotal mediators of type 2 inflammation in asthma." (PMID 41374409, 2025). "With respect to the immunology of asthma pathogenesis, Th2 cytokines such as IL-4, IL-5, IL-9, and IL-13 are considered key mediators in the development of airway inflammation and AHR." (PMID 39949968, 2025). "The current biologics for severe asthma treatment include omalizumab (anti-IgE), mepolizumab and reslizumab (anti-IL-5), benralizumab (anti-IL-5 receptor), dupilumab (anti-IL-4/IL-13), and tezepelumab (anti-TSLP)." (PMID 40364184, 2025). "In the IL-13 antibody group, ocular pruritus and conjunctivitis were the most frequently reported symptoms, followed by single reports of fatigue, asthma exacerbation, and grade 3 eosinophilia." (PMID 40861471, 2025). "Due to its blockage of the cytokine-induced damage, dupilumab is commonly used to treat diseases that utilize the IL-4 and IL-13 pathway, including asthma, atopic dermatitis, chronic sinusitis with nasal polyps, and eosinophilic esophagitis." (PMID 40861695, 2025). "Upon stimulation, they produce IL-5 and IL-13, thus contributing to the progression of changes in asthma." (PMID 40723867, 2025). "Collectively, these findings suggest that targeting IL-4 or IL-13 individually is insufficient to achieve asthma control, highlighting the need for alternative strategies." (PMID 41145900, 2025). "In asthma, several cytokines such as IL-4, IL-5, IL-13, and VEGF play key roles in disease pathogenesis by promoting airway eosinophilia, mucus overproduction, bronchial hyperresponsiveness, immunoglobulin synthesis, and angiogenesis." (PMID 40506894, 2025). "In the respiratory system, IL-13 enhances airway hyperreactiveness and mucus production, thus contributing to the pathogenesis of asthma hallmarks." (PMID 40723867, 2025). "In contrast, elevated FeNO in asthma reflects eosinophils, which release toxic potent inflammatory cytokines such as IL-4, IL-5, and IL-13 that induce airway alterations termed sensitization and swelling." (PMID 40662069, 2025). "In this study, we investigate the link between IL-13 and epithelial interferon responses to viruses in pediatric asthma." (PMID 41427379, 2025). "Meng and Zhu found that administration of recombinant human IL-37 protein, either via intranasal inhalation or intravenous injection, effectively reduced levels of IL-4, IL-5, IL-6, and IL-13 in a chronic HDM-induced asthma model." (PMID 41293155, 2025). "A large portion of pediatric asthma is Type-2 (T2) asthma, which is characterized in part by IL-13 driven airway inflammation." (PMID 41427379, 2025). "When various biological agents relate to IgE, thymic stromal lymphopoietin (TSLP) and Th2 cytokines (IL-4, IL-5, IL-13) are added to intensive controller medications; these agents are somewhat effective for a subgroup of patients with severe asthma." (PMID 40001485, 2025).
asthma (continued). "Research focusing on the expression of ACE-2 and TMPRSS2 in the presence of IL-13 was conducted by collecting airway epithelial cells from patients with asthma via bronchoscopy." (PMID 40004141, 2025). "From a physiological mechanism perspective, estrogen exerts a direct protective effect on asthma by inhibiting Th2-type inflammatory responses (e.g., reducing the release of IL-4, IL-5, and IL-13) and lowering airway hyperresponsiveness." (PMID 41244254, 2025). "The imbalance between Th2 and Th1 lymphocytes represents a predominant etiology of asthma, leading to over-production of Th2 cytokines (IL-4, IL-5, IL-13) and a decrease in IFN-γ, driving the pathophysiological changes in asthma." (PMID 40420184, 2025). "ROC curve analysis shows that IL-13 has a high accuracy in predicting poor asthma control, with areas under the curve of 0.741." (PMID 40260311, 2025). "The hallmark of the Th2-high asthma was IL4, IL5, and IL13, and the mouse Elisa kit was used to screen the Th2 cytokines in BALF and serum of different stages mouse models first (data not shown)." (PMID 40503233, 2025). "Type 2 (T2) inflammation represents the predominant immunological pathway in asthma and is characterized by eosinophilic airway infiltration together with Th2-dependent overproduction of cytokines such as IL-4, IL-5, and IL-13." (PMID 41515904, 2025). "IL-4 and IL-13 play crucial roles in many aspects of airway changes in asthma, whereas IL-5 supports the development and amplification of eosinophilic inflammation and the induction of airway remodeling." (PMID 39962262, 2025). "In terms of predictors for poor asthma control, this study found that IL-13 demonstrated high accuracy." (PMID 40260311, 2025). "Dupilumab, a human mAb that binds to IL-4Rα, inhibits both IL-4 and IL-13 signaling and reduces asthma exacerbations, decreases oral corticosteroid (OCS) dosage, and improves lung function and symptom control in patients with asthma." (PMID 40810090, 2025). "IL-13 is a key mediator in allergic inflammation, particularly in respiratory allergy and asthma, while IL-10 plays a role in immune tolerance and anti-inflammatory responses." (PMID 40944184, 2025). "T2-high asthma is seen in around 50% of patients, who typically have eosinophilic inflammation mediated by cytokines including IL-4, IL-5, and IL-13, with enhanced levels of immunoglobulin E (IgE) often present." (PMID 41440490, 2025). "In parallel, strategies aimed at IL-13 blockade have been used with the hope that interfering with this cytokine would relieve patients with T2high asthma symptoms." (PMID 41145900, 2025). "Anti-IL-13 agents, such as lebrikizumab or tralokinumab, are also being investigated for asthma, in addition to COPD, due to their involvement in mediating T-cell responses after their release from ILCs and in mediating airway hypersensitivity." (PMID 39861052, 2025). "This suggests that GEB treatment has an anti-inflammatory and anti-allergic effect by reducing the levels of IgE and the cytokines IL-4, IL-5, and IL-13 and ameliorating histopathological changes in an asthma rat model." (PMID 40958130, 2025). "Significant differences were observed in IL-6, IL-10, IL-13, 25-(OH) D3 levels, and leptin among children with asthma combined with obesity/overweight and those with asthma or obesity/overweight alone." (PMID 40083433, 2025). "IL-13 is a key mediator in airway remodelling, mucus hypersecretion, and inflammation, and its modulation is crucial for long-term asthma control." (PMID 40951891, 2025). "In an asthma exacerbation model induced by poly I:C, the reduction of inflammatory mediators such as IL-13 and IL-9 can significantly alleviate airway inflammation and hyperresponsiveness." (PMID 40636260, 2025). "IL-36β, IL-36γ, IL-36Ra, and IL-38 were also positively correlated with IL-13 in our asthma patients." (PMID 40115968, 2025).
asthma (continued). "Both IL-4 and IL-13 can contribute to many of the observed airway changes seen in asthma, including airway hyperreactivity, goblet cell hyperplasia, mucous production, smooth muscle proliferation, and subepithelial basement membrane thickening." (PMID 39586024, 2025). "Among these, Type 2-high (Th2-high) asthma is the most well-characterized in both children and adults, driven by IL-4/IL-5/IL-13-mediated eosinophilic inflammation and elevated fractional exhaled nitric oxide (FeNO)." (PMID 40503233, 2025). "PF-07275315 (Tilrekimig) is a trispecific antibody targeting TSLP, IL-4, and IL-13 currently in phase 2 clinical development for the treatment of asthma (NCT06977581) and atopic dermatitis (NCT05995964)." (PMID 41409758, 2025). "Eosinophilic activation, survival, and recruitment, which are commonly observed in asthma, are greatly mediated by IL‐13 action, and increased levels of IL‐13 mRNA were observed in the sputum and airway mucosa samples of patients with eosinophilic disorders." (PMID 40568744, 2025). "In the lung, inhibition of FOXM1 prevents IL-13 mediated goblet cell hyperplasia in murine asthma models." (PMID 40501685, 2025). "Dupilumab, initially approved for atopic dermatitis and asthma, blocks IL-4 and IL-13 signaling and has shown promising results in BP, especially in severe cases or when traditional therapies fail." (PMID 41143232, 2025). "In an IL-4/IL-13-enriched environment, as in asthma, apoptotic neutrophils induced a tissue remodeling macrophage phenotype and apoptotic epithelial cells induced a tolerogenic macrophage phenotype." (PMID 41246133, 2025). "Asthma, marked by inflammation driven by type 2 helper T (Th2) cells and cytokines like IL-4, IL-5, and IL-13, also involves Th17 cells and IL-17 in more severe instances." (PMID 40661126, 2025). "An in vivo mouse model revealed that IL-13 from ILC2s leads to bronchial epithelial barrier disruption by regulating TJs in experimental asthma pathogenesis." (PMID 41303221, 2025). "In the current study, we found significant differences between males and females with asthma in the number of eosinophils and ILC2s, levels of IL‐13, TSLP, soluble ST2 (sST2) and ST2L expression on ILC2s in the airways." (PMID 40022441, 2025). "ILC2 and Th2 cells secrete large amounts of type 2 cytokines (T2), IL-4, IL-5, and IL-13, which are key drivers of asthma pathogenesis." (PMID 40370530, 2025). "A third antibody targeting IL-13, tralokinumab, has undergone phase 1, 2 and 3 clinical trials in patients with severe uncontrolled asthma." (PMID 41145900, 2025). "Type 2 cytokines, such as: IL-4, IL-5 and IL-13, as well as IL-8 play a significant role in asthma development." (PMID 40389545, 2025). "In experimental studies, it was found that the IL-4 and IL-13 functions were positively correlated at the molecular level and in asthma." (PMID 40953067, 2025). "In vitro cytokine responsiveness to microbial products was impaired in cells from neonates born to mothers with the lowest IFN‐γ:IL‐13 ratio, suggesting that neonatal innate immunity was defective in infants who developed asthma during childhood." (PMID 39625247, 2025). "Serum periostin is generated by airway epithelial cells in response to IL-13 and is a marker of T2-related airway inflammation in patients with asthma." (PMID 40863432, 2025). "Dupilumab (DUP) is a monoclonal antibody that inhibits interleukin IL-4 and IL-13 signaling and is approved for type 2 Inflammatory Disease such as asthma, chronic rhinosinusitis with nasal polyposis and atopic dermatitis." (PMID 39798025, 2025). "Group 2 innate lymphoid cells (ILC2s) promote the recruitment of eosinophils by secreting large amounts of type 2 cytokines (IL-5 and IL-13), thus triggering the main feature of asthma, pathological inflammation." (PMID 40451928, 2025).
asthma (continued). "T helper 2 cells (Th2 cells) responses play a central role in asthma pathogenesis, by activating cytokines like interleukin (IL)-4, IL-5, IL-9, and IL-13, which promote eosinophil infiltration into airway wall and excessive mucus production." (PMID 41040870, 2025). "It is a fully human mAb targeting the IL-4 receptor alpha (IL-4Rα) and IL-13 and has significantly advanced the treatment landscape for patients with moderate-to-severe asthma, particularly those with type 2 inflammation." (PMID 40564060, 2025). "More importantly, ILC2s were suggested one of the major sources of steroid-resistant IL-4 and IL-13 transcripts in mice models of steroid-resistant asthma exacerbation." (PMID 40236701, 2025). "IL-13 is a key driver of Th2-mediated asthma, and it promotes airway hyperresponsiveness, mucus overproduction, and eosinophilic inflammation, making it a major contributor to airway remodeling and asthma severity." (PMID 41256924, 2025). "Approved asthma biologic antibodies target critical points surrounding the T2 immune response including T2 cytokine signaling (IL-4, IL-5, and IL-13), downstream T2 response (IgE), and upstream T2 initiation [thymic stromal lymphopoietin (TSLP)]." (PMID 39586024, 2025). "Salidroside has also been reported to alleviate inflammatory cell infiltration in OVA-induced asthma mouse models, suppress IL-4, IL-5, and IL-13 expression, and reduce phosphorylation of Akt and GSK3β." (PMID 40490797, 2025). "After switching to dupilumab (IL-4/IL-13 inhibitor), both cAEs and asthma improved, with complete resolution within two months." (PMID 41393760, 2025). "As both elevated TSLP and ILC2 numbers indicate a type 2 response, we measured the type 2 cytokine IL‐13 in bronchial lavage and found that females with asthma exhibited higher levels of IL‐13 than males with asthma." (PMID 40022441, 2025). "Furthermore, evidence has identified that IL-13 and other Th2 cytokines are key drivers of allergic inflammation and the patho-physiological changes in asthma, but may also be linked to reduced ACE-2 expression in asthmatic airway cells and an increase in transmembrane serine protease 2 (TMPRSS2)." (PMID 40004141, 2025). "Biologic therapies targeting the IL-4/IL-13 pathway, such as anti-IL-4Rα monoclonal antibodies (mAbs), have shown improvements in lung function and reductions in exacerbation rates for severe asthma." (PMID 40370530, 2025). "Th2-high asthma, characterized by elevated levels of IL-4, IL-5, and IL-13 alongside eosinophilic infiltration, typically demonstrates favorable responses to corticosteroids and specific biologics." (PMID 41394843, 2025). "For example, the anti‐IL13 biologic tralokinumab is effective in atopic dermatitis and is approved for this indication, but tralokinumab failed as a treatment for asthma during phase II." (PMID 40662227, 2025). "IL-13, secreted by type-2 helper cells (TH2) upon stimulation, has been linked to increased asthma susceptibility and elevated levels of immunoglobulin-E (IgE)." (PMID 39744511, 2025). "Obesity-related asthma is associated with a Th1 immune response (involving TNF-α, IFN-γ, IL-6, and IL-8) rather than a Th2 response (which involved IL-4, IL-5, IL-10, and IL-13)." (PMID 40083433, 2025). "Anrukinzumab, a humanized anti-IL-13 antibody, was used in patients with mild asthma, and although initial studies reported some increase in lung function, the antibody was discontinued because of its limited effectiveness in patients with uncontrolled asthma." (PMID 41145900, 2025). "Proinflammatory cytokines (TNF-α, IL-6) and profibrogenic mediators (TGF-β1, IL-13) also play significant and distinct roles in asthma pathogenesis." (PMID 40573126, 2025). "Collectively, these results underscore the pivotal role of STAT3 in driving ferroptosis and inflammatory responses in IL-13-treated 16HBE cells, offering new insights into the pathogenesis of asthma." (PMID 40165005, 2025).